PCSK9 (proprotein convertase subtilisin/kexin type 9)
Diseases named in the same sentence as PCSK9 in open-access papers (continued):
Sharing a sentence is not in itself a finding about the gene and the disease.
atherosclerosis (continued). "Moreover, given atherosclerosis as the most prevalent underlying condition, it is unknown whether aggressive lipid lowering therapies with PCSK-9 inhibitors might provide a prognostic benefit in CAE patients with ACS." (PMID 35187112, 2021). "Given that some immunotherapies (e.g., CD20-, EGFR-, IL-1β- or PCSK9-targeting antibodies) were shown to protect from both cancer and atherosclerosis, inflammatory processes and immunity underlying carcinogenesis and atherogenesis may be closely interconnected." (PMID 35097027, 2021). "Thus, PCSK9 deficiency protects Apoe−/− mice from developing atherosclerosis." (PMID 29495280, 2018). "Treatment with PCSK9 inhibitors has been proven effective in reducing the volume of atherosclerosis, leading to plaque regression and enhanced stability." (PMID 41601579, 2026). "PCSK9 regulates LDL-C, a major atherosclerosis risk factor, and contributes to plaque progression through lipid accumulation, inflammation, and apoptosis." (PMID 41590245, 2026). "PCSK9 was shown as a crucial player in hypercholesterolaemia and atherosclerosis pathophysiology, while its inhibition decreased the level of LDL-C, reduced the inflammation response in the arterial wall and attenuated atherosclerotic plaque development." (PMID 39364866, 2025). "Recent studies show that PCSK9 plays an important role in the atherosclerosis progression beyond regulating the plasma LDL-C levels." (PMID 40653676, 2025). "In the context of atherosclerosis, PCSK9 emerges as a key player in the development and progression of degenerative vascular disease, particularly in coronary arteries, by influencing LDL cholesterol levels and inflammation." (PMID 40354375, 2025). "This study demonstrates a comprehensive computational approach to identify and analyze potential small-molecule inhibitors targeting PCSK9, a critical regulator of LDL-c levels implicated in atherosclerosis and cardiovascular diseases." (PMID 40733228, 2025). "Further investigations are necessary to fully elucidate the involvement of PTX3 in the pathophysiology of atherosclerosis and the influence of different PCSK9 inhibitors on PTX3 plasma levels." (PMID 40573228, 2025). "Gain‐of‐function mutations (e.g., D374Y, S127R) amplify PCSK9 activity, causing autosomal dominant hypercholesterolemia (LDL‐C > 190 mg/dL) and accelerating atherosclerosis progression." (PMID 41190281, 2025). "Beyond its role in atherosclerosis, PCSK9 enhances platelet reactivity by upregulating lipid‐mediated signaling pathways, thereby increasing blood hypercoagulability and thrombosis susceptibility." (PMID 41190281, 2025). "In the context of atherosclerosis, PCSK9 is expressed by various cell types within the vascular wall, including endothelial cells, smooth muscle cells, and macrophages, and is found within atherosclerotic plaques." (PMID 40764605, 2025). "The antioxidant properties of PCSK9 inhibition have also been confirmed in other models, including human studies on atherosclerosis-related vascular damage and in rats with post-alcoholic liver fibrosis treated with monoclonal antibodies." (PMID 41009504, 2025). "Overexpression of PCSK9 in mice leads to decreased hepatic LDL-R levels and elevated serum cholesterol, while PCSK9 gene inactivation slows atherosclerosis progression." (PMID 40362720, 2025).
atherosclerosis (continued). "Ox-LDL, in turn, can induce the overexpression of PCSK9, further advancing the progression of atherosclerosis, and thereby establishing a positive feedback loop that promotes atherosclerotic development." (PMID 40354375, 2025). "Young (3 months) and aged (18 months) male C57Bl/6 mice received a single i.v. injection of a recombinant adeno-associated virus encoding murine PCSK9 (rAAV8-D377Y-mPCSK9) and were fed a Western-type diet (WTD) for 10 weeks to induce atherosclerosis." (PMID 40603813, 2025). "Long non-coding RNA (lincRNA) p21 is involved in the development of atherosclerosis, and competitively binds to miR-221 to promote the deacetylation of Pcsk9 by SIRT1, thereby reducing the progression of atherosclerosis." (PMID 40710369, 2025). "PCSK9, a known contributor to atherosclerosis, has been identified as contributing to cellular migration." (PMID 40354375, 2025). "PCSK9 inhibitors and Lp(a)-lowering RNA-based therapies represent two promising pharmacological strategies with therapeutic potential in both atherosclerosis and calcific aortic valve stenosis." (PMID 40943088, 2025). "Red watermelon has potential in atherosclerosis prevention by modulating the expression of PCSK9, LOX-1, CD36, ROS, TNFα, and ABCA1." (PMID 40699832, 2025). "A promising approach to gene therapy for atherosclerosis is also the inactivation of the secreted enzyme Pcsk9, which destroys lipoprotein receptors." (PMID 40725196, 2025). "Although PCSK9 inhibitors have been widely studied for their role in cholesterol regulation and atherosclerosis management, their effects on lysosomal function remain largely unexplored." (PMID 40426881, 2025). "The therapeutic approaches targeting PCSK9 have been developed due to the effects of PCSK9 on atherosclerosis." (PMID 40823653, 2025). "on the mechanism by which homocysteine (Hcy) accelerates atherosclerosis further revealed a fundamental link between PCSK9 and HDL function." (PMID 41478627, 2025). "Currently treatments for atherosclerosis include statins, PCSK9 inhibitors, and antiplatelet and anti-inflammatory agents." (PMID 39920588, 2025). "As a result, elevated PCSK9 activity leads to increased circulating LDL-C levels, contributing to a higher risk of atherosclerosis and cardiovascular disease." (PMID 40942107, 2025). "The transgenic Yucatan hypercholesterolemic minipig overexpressing proprotein convertase subtilisin/kexin 9 (PCSK9) consistently develops human-like atherosclerosis when placed on a high fat high cholesterol diet." (PMID 40131655, 2025). "The atherosclerosis control group (K+) exhibited significantly elevated PCSK9 and foam cell formation, alongside suppressed ABCA1 expression, indicating enhanced atherosclerotic progression." (PMID 40699832, 2025). "The design of small-molecule inhibitors targeting proprotein convertase subtilisin/Kein type 9 (PCSK9) remains a forefront challenge in combating atherosclerosis." (PMID 40733228, 2025). "Monoclonal antibodies have been developed to decrease PCSK9 levels, which protect individuals from atherosclerosis and ischemic heart disease." (PMID 39928272, 2025).
atherosclerosis (continued). "Preclinical studies in APOE*3Leiden.CETP transgenic mice, a well‐established model of atherosclerosis, revealed that PCSK9 gene knockdown exerts potent anti‐inflammatory effects." (PMID 41190281, 2025). "Currently, lipid-lowering drugs (including statins and PCSK9 inhibitors) are the standard therapeutic agents for atherosclerosis." (PMID 40635740, 2025). "Renin (REN), NT-proBNP, Natriuretic peptide B (NPPB), and proprotein convertase subtilisin/kexin type 9 (PCSK9) consistently emerged as the top contributors to the atherosclerosis-related, MR-derived, and whole proteome panels." (PMID 40585252, 2025). "This underscores the critical role of PCSK9 in the development and progression of atherosclerosis, with potential implications for therapeutic interventions targeting this pathway." (PMID 40354375, 2025). "The association between PCSK9 and inflammation provides a compelling rationale for the therapeutic use of PCSK9 inhibitors in preventing atherosclerosis and its severe consequences, such as myocardial ischemia." (PMID 40354375, 2025). "Proprotein convertase subtilisin/kexin type 9 (PCSK9): PCSK9 can irreversibly bind to LDL receptors, elevating its levels and increasing the risk of atherosclerosis and cardiovascular events." (PMID 40001586, 2025). "The data demonstrated that the PCSK9 H8—“TGAG” haplotype, with three risk alleles for atherosclerosis, had a similar frequency in the two populations; however, we observed that females presented a higher frequency (2.9%) than males (1.8%; p = 0.723)." (PMID 40864779, 2025). "The aim of this study was to determine the best PCSK9 vaccine design for improving dyslipidemia and atherosclerosis in animal studies." (PMID 41346351, 2025). "The findings of this study suggest that an increase in PCSK9 during acute conditions primarily influences the development of myocardial infarction (MI) and atherosclerosis through lipids and LDL-C." (PMID 40357205, 2025). "Here the authors show that PCSK9 itself directly induces inflammation and aggravates atherosclerosis independently of the LDL receptor." (PMID 38555386, 2024). "PCSK9 inhibitors are primarily used in clinical settings for treating high cholesterol, atherosclerosis, and related heart-related conditions, showing substantial efficacy and potential as alternatives to statins and Evolocumab." (PMID 39770423, 2024). "A recent paper indeed shows that atherosclerosis induction by PCSK9-AAV administration results in increased inflammation and lesion area in mice that lack ACOD1, and the authors propose an important role of NRF2 in mediating this phenotype." (PMID 38309122, 2024). "A surprising finding from sequencing analysis was that people with gain‐of‐function mutations in PCSK9 had more LDL receptors destroyed, which increased LDL‐C levels and increased the risk of atherosclerosis." (PMID 39479289, 2024). "Non-coding RNAs (ncRNA) play a crucial role in the progression of inflammation in atherosclerosis by targeting genes related to the PCSK9 pathway at the post-transcriptional level." (PMID 38895538, 2024). "Here, we identified a pivotal mechanism for how PCSK9 directly induces inflammation and aggravates atherosclerosis independently of the changes in lipid levels." (PMID 38555386, 2024). "Here we show that PCSK9 itself directly induces inflammation and aggravates atherosclerosis independently of the LDL receptor." (PMID 38555386, 2024).
atherosclerosis (continued). "Wild‐type Sirt3f/f mice and endothelium‐selective SIRT3 knockout Sirt3f/f; Cdh5Cre/+ (Sirt3EC‐KO) mice are injected with adeno‐associated virus (AAV) to overexpress PCSK9 and fed with high‐cholesterol diet (HCD) for 12 weeks to induce atherosclerosis." (PMID 38233193, 2024). "Most of the clusters and their synonyms can also be found in the co-occurrence analysis, such as “omega-3 fatty acids” (# 0), “atherosclerosis” (# 1), “simvastatin” (# 2), “pravastatin” (# 4), “PCSK9” (# 8), and “ezetimibe” (# 10)." (PMID 38828451, 2024). "The plasma level of PCSK9 was found to be positively correlated with platelet counts in patients with coronary artery disease, suggesting that the involvement of PCSK9 in atherosclerosis includes platelet-related mechanisms." (PMID 39767636, 2024). "This study investigates PCSK9 inhibitors, particularly Evolocumab, in treating atherosclerosis by managing LDL-C levels with statin therapy." (PMID 39770423, 2024). "Factors such as lipopolysaccharide, oxidized LDL, TNF-α, and IL-1β have been noted for inducing PCSK9 secretion in various organs, contributing to conditions like hyperlipidemia, atherosclerosis, diabetes, and hypertension." (PMID 38762465, 2024). "Several signaling pathways implicated in the inflammatory response are associated with atherosclerosis, including the NLRP3 inflammasome, TLRs, proprotein convertase subtilisin/kexin type 9, Notch, and Wnt signaling pathways." (PMID 38803504, 2024). "Still, we have previously found that the level of misclassification by standard immune fluorescent staining in PCSK9-induced atherosclerosis is minor as assessed by SMC lineage tracing." (PMID 38234375, 2024). "Results from outside the United States must be thoroughly shared within this study domain for it to be more advantageous, given that the suppression of PCSK9 serves as the foundation in atherosclerosis treatment." (PMID 39247108, 2024). "PCSK9 inhibitors, a novel class of monoclonal antibodies used in atherosclerosis treatment, operate by reducing the deviation of LDL receptors and increasing LDL-cholesterol clearance in the bloodstream." (PMID 38375475, 2024). "The primary objective of this research is to assess the current status of knowledge, research endeavours and developmental trajectories about proprotein convertase subtilisin/kexin type 9 (PCSK9) inhibitors in correlation with atherosclerosis treatment." (PMID 39247108, 2024). "Statins, ezetimibe, and more recently, proprotein convertase subtilisin kexin 9 (PCSK9) inhibitors and bempedoic acid have confirmed the causal role of LDL-c in the development of atherosclerosis." (PMID 38667744, 2024). "Protein convertase subtilisin/kexin type 9 (PCSK9) is a serine protease integral to cholesterol metabolism, atherosclerosis, and cardiovascular health." (PMID 39770439, 2024). "The inhibitors of PCSK9 have been widely recognized in the treatment of atherosclerosis regarding to lipid metabolism." (PMID 38402551, 2024).
atherosclerosis (continued). "This indicates a potential important role of the anti-PCSK9 L-IFPTA+ vaccine in the treatment of existing atherosclerosis." (PMID 38165521, 2024). "While pivotal trials spotlighted the LDL-lowering capabilities of PCSK9 inhibitors, recent studies have focused on the pleiotropic effects of PCSK9 inhibitors on atherosclerosis beyond LDL reduction." (PMID 38817546, 2024). "Except for the importance of lipoproteins in the development of atherosclerosis, another crucial lipid metabolism regulator is PCSK9." (PMID 37530998, 2024). "The findings revealed a direct link between PCSK9 and atherosclerosis, with PCSK9 overexpression significantly inducing atherosclerosis and its deficiency providing cardiovascular protection." (PMID 38185721, 2024). "mRNA-based vaccines targeting inflammation, lipid metabolism, and plaque formation offer a transformative approach to treating atherosclerosis by focusing on molecular pathways like PCSK9." (PMID 39712846, 2024). "In 2014, two research groups separately described the so-called pro-protein convertase subtilisin/kexin type 9 (PCSK9)-adeno-associated virus (AAV) mice as a quick, adaptable, and cost-effective animal model for atherosclerosis." (PMID 38629090, 2024). "Using mRNA-based vaccinations in conjunction with conventional lipid-lowering medications like PCSK9 inhibitors and statins offers an intriguing way to improve the effectiveness of atherosclerosis therapy." (PMID 39712846, 2024). "The consumption of dietary components that inhibit proprotein convertase subtilisin/kexin 9 (PCSK9) can positively influence lipid metabolism during the development and progression of atherosclerosis." (PMID 37997262, 2024). "Human Meg3 transgenic mice were generated to examine the role of Meg3 gain-of-function in the development of atherosclerosis induced by PCSK9 overexpression." (PMID 38518516, 2024). "PCSK9 is abundantly expressed in the cells of arterial walls, such as endothelium, SMCs, and macrophages, which can regulate vascular homeostasis and atherosclerosis." (PMID 38445291, 2024). "Proprotein convertase subtilisin/kexin type 9 (PCSK9) is a key driver of the atherosclerosis process by increasing plasma low density lipoprotein and inducing endothelial dysfunction." (PMID 38172197, 2024). "PCSK9 plays a key role in platelet aggregation and adhesion, endothelial dysfunction and atherosclerosis." (PMID 38887452, 2024). "In the present study, we assessed the importance of SMC-secreted CCL2 for early atherosclerosis in murine atherosclerosis induced by PCSK9 overexpression." (PMID 38234375, 2024). "The objective of the present study was to examine the influence of IKKε on the pathophysiology of atherosclerosis and liver steatosis in the PCSK9/PD model in mice." (PMID 39409049, 2024). "In recent years, it is widely accepted that the association between Proprotein convertase subtilisin/kexin type 9 (PCSK9) and atherosclerosis is dependent on PCSK9-mediated modulation of LDL metabolism." (PMID 38491418, 2024). "These animals were injected with recombinant adeno-associated virus encoding a gain-of-function mutant PCSK9 (AAV-PCSK9) and fed with a Western diet to induce atherosclerosis." (PMID 39643078, 2024). "Nevertheless, inhibition of PCSK9 reduces plasma concentration of low-density lipoprotein cholesterol, atherosclerosis and coronary heart disease, which likely explains its association with heart failure." (PMID 39434187, 2024). "PCSK9 modulates inflammation, atherosclerosis progression, platelet activation, and thrombus formation." (PMID 38817546, 2024).